BCL2 (BCL2 apoptosis regulator)
Diseases named in the same sentence as BCL2 in open-access papers (continued):
Sharing a sentence is not in itself a finding about the gene and the disease.
infection (continued). "On the other hand, Bcl-2 is an antiapoptotic protein whose overexpression is anticipated as a mechanism employed by T. cruzi to inhibit apoptosis, as has been demonstrated during the infection of cardiomyocytes and H9c2 cells." (PMID 40661785, 2025). "The infection with T. cruzi of murine cardiomyocytes cultured in medium with minimal serum concentration showed an increased survival of the cells, which correlated with a rise in Akt phosphorylation and in the expression of Bcl-2." (PMID 40661785, 2025). "Ideally, these observations would be validated in knockout models; however, MYB loss in a c-myb knockout murine model impeded the formation of stem cell-like TCM CD8+ T-cells with loss of Bcl-2 and massive apoptosis of CD8+ T-cells in the initial immune response to infection." (PMID 41232235, 2025). "Following ANXA2 knockdown, the cell apoptosis rate, caspase-3 activity, and Bax expression levels were significantly increased (P < 0.01), whereas the infection rate and Bcl-2 expression levels were significantly decreased (P < 0.01) compared to the group infected with E. tenella alone." (PMID 40777830, 2025). "scRNA-seq of spleen CD8+ TM cells isolated day 7 after LCMVc13 infection showed that anti-apoptotic genes such as Bcl2, Mcl1 and Xiap were diminished, while pro-apoptotic genes like Bax and Bid35,36 were elevated in GFI1ΔCD8 CD8+ T cells compared to WT CD8+ T cells." (PMID 40374731, 2025). "qRT-PCR analysis revealed that gcHnf4α overexpression upregulated the mRNA levels of apoptosis-related genes—aif, caspase 3, caspase 8, caspase 9, bax, and bcl-2—during A. salmonicida mono - infection, indicating potential engagement of both pro- and anti-apoptotic pathways." (PMID 40920830, 2025). "BHRF1 is an EBV gene homologous to Bcl-2, expressed from early infection through the E lytic phase." (PMID 41516315, 2025). "After infection, IκBα is phosphorylated and degraded, releasing the p65 subunit to translocate into the nucleus, which then drives the transcription of pro-inflammatory cytokines and anti-apoptotic genes (e.g., Bcl-2)." (PMID 41475173, 2025). "In the present study it was observed that compared with the control, the relative protein expression levels of caspase-3 and Bax increased significantly, and that the relative expression levels of Bcl-2 protein decreased significantly, following infection of the cells with Pg and Pg-LPS." (PMID 38731952, 2024). "The downregulation of Bcl-2 expression levels and the reduction in the WSSV viral load in this study may indicate that Bcl-2 plays a role in inhibiting host cell infection by WSSV." (PMID 39452067, 2024). "We found that SARS-CoV-2pp infection increased the anti-apoptotic protein BCL2." (PMID 38727305, 2024). "The results shown that the expression of proapoptotic proteins, including Bax, caspase-3, caspase-9 and cytochrome c, increased in the infection group; however, the expression of the antiapoptotic protein Bcl-2 decreased, indicating that apoptosis was induced by GoAstV infection in GEK cells." (PMID 39502173, 2024). "In addition, infection was accompanied by significant changes in the expression of proapoptotic Bax and anti-apoptotic Bcl-2." (PMID 39845048, 2024). "The grouper iridovirus (GIV) vBcl-2, GIV66, has previously been shown to inhibit intrinsic apoptosis by downregulating host pro-death Bcl-2 proteins, localized primarily at the mitochondrial membrane of the host cell and exerting early control over apoptosis during infection." (PMID 38932171, 2024). "Poxviruses and iridoviruses have been associated with sponges, though cellular infection has not been demonstrated yet; thus, from an evolutionary perspective, the accumulation of Bcl-2 genes and their preservation in dsDNA viral genomes is not surprising." (PMID 38932171, 2024).
infection (continued). "In the spleen, there were no obvious changes in the expression of each gene in undernutrition 75% + infection group, and only the apoptosis inhibiting gene Bcl-2 (P = 0.0344) and T cell exhaustion gene Tim-3 (P = 0.0494) were downregulated at the 5th week post-infection." (PMID 38185681, 2024). "However, the protein expression level of the critical antiapoptotic protein Bcl-2 decreased significantly from 12 hpi to 48 hpi in the infection group, which resulted in an increase in the ratio of Bax to Bcl-2." (PMID 39502173, 2024). "Although our Bcl2AAA organoid experiments indicate an epithelial cell autonomous role for BCL2 in restricting bacteria, it is possible that cells other than enterocytes may contribute to the decreased infection resistance in Bcl2AAA mice." (PMID 39602254, 2024). "Studies on the mechanisms of apoptosis caused by P. marinus have shown that early post-infection stimulation of apoptosis is not caspase-dependent but occurs through the mitochondrial pathway (Bcl-2, anamorsine)." (PMID 38792826, 2024). "Moreover, apoptosis is regulated during infection via the B-cell lymphoma (Bcl2) proteins, and cellular stress can trigger apoptosis." (PMID 39408905, 2024). "Third, MVA infection induces apoptosis in dendritic cells via upregulation of Bcl-2 protein NOXA17." (PMID 38065956, 2023). "Our results demonstrated that increasing infection doses could significantly decrease Bcl-2 expression, raise Bax mRNA level, and elevate TNF-α and cleaved caspase-3 protein levels versus control cells." (PMID 37641004, 2023). "The protein implicated in the induction of apoptosis was the antiapoptotic protein Bcl-2 as shown by the downregulation of Bcl-2 RNA or protein in peripheral blood monocytes (PBM) following infection with M. bovis BCG or induction with heat-killed M. tuberculosis H37Ra." (PMID 38112844, 2023). "Compared with B. suis S2 and C∆alr, infection with the ∆alr significantly increased the release of Cytochrome C, decreased the expression of the upstream Bcl2 protein, inhibited the expression of Bax, and significantly reduced the Bcl2/Bax expression ratio." (PMID 37445922, 2023). "This suggests that SARS-CoV-2 relies on BCL-2 for a productive infection." (PMID 36569952, 2022). "However, infection with ΔdotA C. burnetii resulted in down-regulation of Bcl-2 and upregulation of Bax under hypoxia." (PMID 35755850, 2022). "BCL-2 upregulation has been documented by day 4 of infection." (PMID 36569952, 2022). "Furthermore, we analyzed the role of Hh signaling in regulating apoptosis during infection and demonstrate that E. chaffeensis exploits Hh signaling to engage BCL-2 and inhibit apoptosis during infection." (PMID 35576232, 2022). "Thus, OmpA indeed has anti-apoptotic activity that can block apoptosis downstream of anti-apoptotic Bcl-2 proteins, as we had found for Ctr-infection." (PMID 35397654, 2022). "Venetoclax, an existing FDA-approved BCL-2 inhibitor, could be repurposed as an antiviral against viruses that upregulate BCL-2 anti-apoptotic proteins in infection." (PMID 36569952, 2022). "However, DGKζ KO P14 CD8+ T cells expressing a SLEC, MPEC, or TCM phenotype, or Bcl-2 was unaltered by rapamycin treatment at Day 10 post infection." (PMID 36846018, 2022). "Latent proteins not only promote infection through activation of transcription factors like the AP-1, control expression of numerous cytokines, overexpression of BCL-2, but may also promote viral pathogenesis within the host." (PMID 34072365, 2021).
infection (continued). "We examined total cell lysates collected at various time points after infection and found that anti-apoptotic Bcl-2 was downregulated at 72 hrs p.i. and survivin declined at 24 and 72 hrs p.i. in both cell line while FLIP, an inhibitor of pro-caspase-8, remained unchanged." (PMID 33481814, 2021). "Also, the bax transcripts were reduced in infection-IV compared to infection-II, and an increased expression of antiapoptotic gene bcl2 was recorded." (PMID 34585958, 2021). "Rapamycin blocked the infection-induced upregulation of BCL-2 and BCL-Xl, suggesting that modulation of mTOR signaling may be engaged in this reaction." (PMID 33924101, 2021). "Furthermore, we determined a decreased expression of antiapoptotic gene bcl2 in infection-III compared to infection-II." (PMID 34585958, 2021). "Infection with the SopB mutant also resulted in the decrease of Bcl-2 and the increase of Bax in mitochondria, which could be reversed by adding SC79." (PMID 34804044, 2021). "Moreover, Bcl-2 seems to be able to restrict SFV replication by inhibiting early stages of infection and appears to prolong survival of productively infected cells." (PMID 33291372, 2020). "Moreover, it has been shown that rabbit hepatocytes at 36-48 h post infection indicate an increased level of caspase-3 activity and significantly higher expression of the proapoptotic Bax protein compared to the Bcl-2 antiapoptotic protein." (PMID 32878241, 2020). "However, the mRNA expression of anti-apoptotic Bcl2 gene was significantly (p < 0.05) reduced at 3- and 7-day post-infection." (PMID 32391391, 2020). "Moreover, the small-molecule ABT-263 targeting Bcl-2/Bcl-XL was reported to have antiviral properties and facilitate apoptosis induction upon infection, with several DNA and RNA viruses, including MERS-CoV57." (PMID 33072409, 2020). "Stimulated by inflammation and infection, the proapoptosis protein bax and the antiapoptosis protein bcl-2 combined with ANT (adenine nucleotide translocator) or VDAC (voltage-dependent anion channel) competitively, and regulated the switch of the MPTP (mitochondria permeability transition pore)." (PMID 31772700, 2019). "In addition, the overexpression of Bcl-2 in JEV-infected cells was demonstrated to be related to the inhibition of apoptosis at the early stage of infection to facilitate persistent infection." (PMID 31658698, 2019). "Our study demonstrated that upon JEV infection, the induction of apoptotic signal molecules slowly progressed to induce the cell death process at the early stage of infection, which may be due to the protective role of anti-apoptotic Bcl-2 proteins." (PMID 31658698, 2019). "We cultured Bcl-2-expressing CD4+ T cells for 10 weeks to maintain quiescent infection." (PMID 30976083, 2019). "Interestingly, similar to NS1/2 cleavage promoting apoptosis during infection, some Bcl-2 proteins (e.g. Bid) are also regulated via cleavage, in which the truncated version is the active, pro-apoptotic form of the protein." (PMID 31329638, 2019). "After infection, the Bcl-2 protein value declined at 12 h and 24 h in the lean-E." (PMID 31772700, 2019). "Here we found that BCL2 (anti-apoptotic gene) is potentially downregulated by mmu-miR-7667-3p following infection with L. interrogans, leading us to suggest that cell survival could be at risk following L. interrogans infection of macrophages." (PMID 29979677, 2018). "Notably, infection with the AdE1A12S mutant strongly counteracted the mitoxantrone-dependent decreases in Bcl-2 protein levels with a similar trend in Ad∆∆-infected cells at the lowest drug dose (225 nm)." (PMID 29362360, 2018). "While MSP121-specific Bmem from after infection resolution showed the highest levels of expression of the anti-apoptotic Bcl2 gene, MSP121-specific AMB sorted during chronic P. chabaudi infection showed the lowest levels of expression of this hallmark anti-apoptotic gene." (PMID 30387712, 2018).
infection (continued). "These elevated levels of Bcl-2 may lead to diminished death phase after secondary infection, resulting in a net increase in memory cells." (PMID 28407741, 2017). "However, combined infection of MDMs with both pathogens or PRRSV only showed significantly (p < 0.05) lower expression of Bcl-2 mRNA in comparison with H. parasuis only infected MDMs at 4/28 h PI." (PMID 28472979, 2017). "During the early stages of infection, Cryptosporidium inhibits host cell apoptosis by promoting the expression of the anti-apoptotic protein Bcl-2 but decreasing the expression of the pro-apoptotic protein Bax and reducing the release of apoptosis-related mitochondrial proteins." (PMID 29282063, 2017). "Furthermore, F1L only bound a highly restricted subset of pro-apoptotic Bcl-2 including Bim and Bak, and was shown to inhibit Bak activation by functionally replacing Mcl-1 during infection." (PMID 28984827, 2017). "Infection with Pg significantly increased expression of genes related to cell death including Bax-1, caspase-1, -3 and -9 and decreased expression of anti-apoptotic Bcl-2 (2-fold)." (PMID 27124409, 2016). "Constitutive expression of bcl-2 also decreased the cell death in BMDMs infected with L. pneumophila, and S. pyogenes when examined with a fixable live/dead stain 24 hours after infection." (PMID 27973535, 2016). "Therefore, to determine the relationship between pPI3K, pAkt, pERK1/2, and Bcl-2 induction during infection, specific pharmacological inhibitors were used to block the kinase activities of the proteins leading to phosphorylation of PI3K, Akt, and ERK1/2." (PMID 27826299, 2016). "Similarly, functional inhibition of Bcl-2 by ABT-199 or ABT-263 led to a significant induction of iNOS post infection." (PMID 27826299, 2016). "qRT-PCR results showed that Bcl2 in the 5b WT-infected PAMs was first downregulated and then subsequently upregulated; Bcl2 expression was significantly lower in 5b ΔAdh-infected PAMs 2 h post-infection (p < 0.01)." (PMID 27046446, 2016). "Our results indeed supported this hypothesis where infection-induced expression of Bcl-2 was shown to be majorly regulated by the IL-13-JAK2-STAT-3 axis." (PMID 27826299, 2016). "A time-dependent increase in Bcl-2 was observed post infection." (PMID 27826299, 2016). "Infection with the ΔespC mutant complemented with either espC or espCS256I also decreased the Bcl-2 protein band intensity at wild-type levels, suggesting that the serine protease motif could not be require for this mechanism." (PMID 27329750, 2016). "Compared with transfection of synthetic mimics, both overexpression of miR-34a and downregulation of Bcl-2 by VV-miR-34a infection were significantly higher than that of synthetic mimics, which supports OVV as an ideal delivery system for miR-34a replacement in MM." (PMID 27552933, 2016). "Using both in vitro and in vivo experimental systems, we, demonstrate increased expression of the Bcl-2 protein in response to L. donovani infection and also show that suppression or functional inhibition of the infection-induced Bcl-2 results in accelerated clearance of the parasites." (PMID 27826299, 2016). "However, Bcl-2 knocked down macrophages showed increased cell death as compared with control cells at 72 h post-infection." (PMID 27826299, 2016). "Infection of macrophages with M. tuberculosis in the presence of Nef further inhibited apoptosis with a significant decrease in Annexin V levels and a sharp increase in Bcl2." (PMID 26132135, 2015). "Peripheral blood CD8 T cells were activated (determined by Ki67 and CD38 expression) in response to infection and expressed perforin, granzyme B, HLA-DR, PD-1, T-bet and Eomes together with low levels of Bcl-2 at day 7 after hospitalization, phenotypically defining these as effector cells." (PMID 25611738, 2015). "However, compared with H2O2 group, such high levels of Bax/Bcl-2 was completely abolished by treatment with FrzA infection." (PMID 26282432, 2015).
infection (continued). "Using MHV68 mutant viruses, we found that vBcl-2 played a critical role in infection of immature and transitional B cells in vivo which could be complemented by host Bcl-2." (PMID 24516386, 2014). "The expression of Bcl-2 gene, after 24 hours, differed according to the strains used to infection." (PMID 25299837, 2014). "As before, HoxB8 infection immortalized Bcl-2−/− progenitor cells." (PMID 24177192, 2013). "Moreover, there was very little alteration on mRNA and protein levels of Bax and Bcl-2 after infection with NDV." (PMID 22935147, 2012). "Echo30 infection also reduced anti-apoptotic protein Bcl-2 expression." (PMID 22586486, 2012). "Several reports have shown that an increased neuronal expression of Bcl-2, Beclin, Bax and decreased expression of Apaf-1 on fibroblast turned cells more resistant to apoptotic cell death induced by SinV infection." (PMID 22485151, 2012). "Therefore, there is a high probability that RTA contributes to virus lytic replication through the activation of cellular Bcl-2 expression very early during infection." (PMID 21901143, 2011). "Infection of TIEG1−/− precursors with AdTIEG suppressed Bcl2 mRNA and protein levels." (PMID 21423731, 2011). "The expression level of Fas, FasL, Bcl-2, Bcl-xL and Bak was assessed by immunohistochemistry and RT-PCR whereas caspases 3, 8 and 9 were assessed by colorimetric assay kits up to 135 days post infection." (PMID 21781333, 2011). "However, we noted that Bcl-2 and related genes were also dysregulated in patients with infection, but to a lesser extent than in septic patients." (PMID 21711552, 2011). "Further, our data suggests that absence of IL-15 alone may play a minor role in committing CD8+CD44int/hiCD127hi T cells to express Bcl-2 during the acute phase of infection." (PMID 20520779, 2010). "Moreover, Bcl-2 expression clearly decreases at 21 hr post-infection when ATP production and ND4 expression is optimally increased." (PMID 19725950, 2009). "Altmann and Hammerschmidt showed that immediate inhibition of apoptosis is an essential requirement following in vitro infection of primary B cells and that the two viral homologues of Bcl-2, BHRF1 and BALF1, were transiently expressed during the early stages of transformation." (PMID 19619657, 2009). "Presence of a duplicated subgenomic promoter or IRES element following the Bcl-2 encoding sequence did not have any major effect on the time-course of infection, however, differences in expression levels of the first marker protein, d1EGFP, were observed." (PMID 17904678, 2008). "An in vivo role during infection has been demonstrated only for the γHV68 v-Bcl-2." (PMID 16201011, 2005). "SGR/AAA v-Bcl-2 mutant viruses displayed normal growth in fibroblast cells in vitro, and replicated normally in the spleen and liver (unpublished data) of infected mice at 4 and 9 d post-infection (dpi)." (PMID 16201011, 2005). "However, the anti-apoptotic Bcl-2 protein showed significantly lower expression in Z12 compared to the Control group, indicating significant inhibition of the anti-apoptotic pathway in the host intestine following strain Z12 infection." (PMID 39945531, 2025). "However, Bcl2, an apoptosis inhibitor, increased significantly from 3 h after infection until 24 h after infection, suggesting that S. aureus-induced apoptosis might be blocked by Bcl2." (PMID 33924622, 2021). "A previous study from our group has shown that BCL2 is a potentially down-regulated by mmu-mir-7667-3p following infection with L. interrogans, suggesting that cell survival could be compromissed after macrophages infection by the spirochete." (PMID 31800570, 2019).